CTR9 (CTR9 component of Paf1/RNA polymerase II complex)
Description:
Component of the PAF1 complex (PAF1C) which has multiple functions during transcription by RNA polymerase II and is implicated in regulation of development and maintenance of embryonic stem cell pluripotency. PAF1C associates with RNA polymerase II through interaction with POLR2A CTD non-phosphorylated and 'Ser-2'- and 'Ser-5'-phosphorylated forms and is involved in transcriptional elongation, acting both independently and synergistically with TCEA1 and in cooperation with the DSIF complex and HTATSF1. PAF1C is required for transcription of Hox and Wnt target genes. PAF1C is involved in hematopoiesis and stimulates transcriptional activity of KMT2A/MLL1; it promotes leukemogenesis through association with KMT2A/MLL1-rearranged oncoproteins, such as KMT2A/MLL1-MLLT3/AF9 and KMT2A/MLL1-MLLT1/ENL. PAF1C is involved in histone modifications such as ubiquitination of histone H2B and methylation on histone H3 'Lys-4' (H3K4me3). PAF1C recruits the RNF20/40 E3 ubiquitin-protein ligase complex and the E2 enzyme UBE2A or UBE2B to chromatin which mediate monoubiquitination of 'Lys-120' of histone H2B (H2BK120ub1); UB2A/B-mediated H2B ubiquitination is proposed to be coupled to transcription. PAF1C is involved in mRNA 3' end formation probably through association with cleavage and poly(A) factors. In case of infection by influenza A strain H3N2, PAF1C associates with viral NS1 protein, thereby regulating gene transcription. Required for mono- and trimethylation on histone H3 'Lys-4' (H3K4me3) and dimethylation on histone H3 'Lys-79' (H3K4me3). Required for Hox gene transcription. Required for the trimethylation of histone H3 'Lys-4' (H3K4me3) on genes involved in stem cell pluripotency; this function is synergistic with CXXC1 indicative for an involvement of the SET1 complex. Involved in transcriptional regulation of IL6-responsive genes and in JAK-STAT pathway; may regulate DNA-association of STAT3 (By similarity).
Synonyms: KIAA0155; SH2BP1; TSBP; p150TSP; p150
Tractability: PROTAC: ubiquitination databases record sites on it; its protein half-life has been measured.
Gene: Protein-coding gene on chromosome 11 (10,751,018 to 10,801,625, forward strand). Ensembl gene ENSG00000198730.
Subcellular location: Nucleus speckle
Subcellular location (Human Protein Atlas): Nucleoplasm
Pathways (Reactome):
Gene expression (Transcription): Formation of RNA Pol II elongation complex; RNA Polymerase II Pre-transcription Events; RNA Polymerase II Transcription Elongation
Chromatin organization: CHD1 and CHD2 subfamily
Disease: Dengue virus activates/modulates innate and adaptive immune responses
Metabolism of proteins: E3 ubiquitin ligases ubiquitinate target proteins
Gene Ontology:
Molecular function: protein binding; RNA polymerase II complex binding; SH2 domain binding
Biological process: negative regulation of myeloid cell differentiation; positive regulation of transcription by RNA polymerase II; stem cell population maintenance; transcription elongation by RNA polymerase II; cell surface receptor signaling pathway via JAK-STAT; cellular response to lipopolysaccharide; endodermal cell fate commitment; interleukin-6-mediated signaling pathway; negative regulation of transcription by RNA polymerase II; chromatin organization; regulation of DNA-templated transcription; regulation of transcription by RNA polymerase II
Cellular component: Cdc73/Paf1 complex; nucleoplasm; nucleus; euchromatin; nuclear speck
Genetic constraint (gnomAD): Loss-of-function variants: 34 observed, 123.03 expected, observed/expected ratio (o/e) 0.28, 90% interval 0.21 to 0.37. The upper end of that interval is the gene's LOEUF score, 0.37, which puts it in group 1 of 6, group 1 being the genes least tolerant of losing a copy. Missense variants: 764 observed, 1,220.9 expected, observed/expected ratio (o/e) 0.63, 90% interval 0.59 to 0.66. Synonymous variants: 399 observed, 440.24 expected, observed/expected ratio (o/e) 0.91, 90% interval 0.83 to 0.99.
Gene-disease validity (ClinGen):
ClinGen rates the evidence that CTR9 causes each of these diseases.
CTR9-related neurodevelopmental disorder (autosomal dominant): Moderate. Any neurodevelopmental disorder in which the cause of the disease is a variation in the CTR9 gene.
Homologues: Orthologues: chimpanzee CTR9 (99% identical), macaque CTR9 (99% identical), dog CTR9 (98% identical), rabbit CTR9 (98% identical), rat Ctr9 (98% identical), mouse Ctr9 (98% identical), guinea pig CTR9 (97% identical), pig CTR9 (97% identical), tropical clawed frog ctr9 (87% identical), zebrafish ctr9 (86% identical), Drosophila melanogaster Ctr9 (59% identical), Caenorhabditis elegans ctr-9 (40% identical).
Diseases named in the same sentence as CTR9 in open-access papers:
CTR9 is named in the same sentence as 16 diseases in open-access papers, as found by Europe PMC text mining. Sharing a sentence is not in itself a finding about the gene and the disease. The quoted sentences say what the papers report.
Wilms tumor (7 papers, 2015 to 2025). An embryonal neoplasm characterized by the presence of epithelial, mesenchymal, and blastema components. "For example, germline mutations in CTR9 were identified in Wilms tumor families, implicating CTR9 as a Wilms tumor predisposition gene." (PMID 35137163, 2022). "CTR9 was first reported as a Wilms tumor predisposition gene, and the mutations are almost truncated." (PMID 31214250, 2019). "Whether H3K27me3 is elevated in CTR9-mutated Wilms tumors, and whether CTR9-mutant expressing tumors are sensitive to EZH2 inhibitors, awaits investigation." (PMID 35137163, 2022). "In addition, a small fraction of familial Wilms tumor cases have been attributed to germline mutations in CTR9." (PMID 29320491, 2018). "Together, these data suggest that the mutations in CDC73 and CTR9 found in patients with hyperparathyroidism-jaw tumor syndrome and some patients with Wilms tumors, respectively, may contribute to cancer progression by contributing to genome instability." (PMID 29320491, 2018). "In particular, PAF1 is involved in pancreatic and ovarian cancer, and CTR9 is involved in Wilms tumor and breast cancer." (PMID 30228257, 2018). "Exon 9 deletion of CTR9 were recently discovered in Wilms tumors." (PMID 35137163, 2022).
breast carcinoma (3 papers, 2016 to 2022). "Specifically, using loss-of-function approach, we observed that depletion of Ctr9 led to apparent morphological change, decrease of proliferation, reduced colony formation, and impaired ERα-target gene expression in ERα-positive breast cancer cells." (PMID 27829357, 2016). "To determine if the Ctr9 signature has a broader clinical significance, we mined breast cancer outcome-linked gene expression data using the Gene Expression-Based Outcome for Breast Cancer Online (GOBO) tool." (PMID 27829357, 2016). "CTR9/PAFc has been shown to regulate ERα mediated transcription via coupling multiple histone modifications in breast cancer cells." (PMID 35137163, 2022). "Knocking down CTR9 in ERα+ breast cancer cells erased >90% of estrogen-regulated transcriptional response, demonstrating CTR9’s function in promoting breast cancer progression." (PMID 35137163, 2022). "This study uncovers that H3K27me3 levels are precisely controlled by CTR9 levels in breast cancer cells." (PMID 35137163, 2022). "As a consequence, CTR9 depletion generates vulnerability that renders breast cancer cells hypersensitive to PRC2 inhibitors." (PMID 35137163, 2022). "Although these findings were made in breast cancer cell lines, the general principal for the establishment of H3K27me3 domains governed by CTR9 is likely conserved in other biological systems (e.g., ESCs)." (PMID 35137163, 2022). "Using inducible and stable CTR9 knockdown breast cancer cell lines, we discovered that the H3K27me3 levels are strictly controlled by CTR9." (PMID 35137163, 2022). "We have found that CTR9 is enriched in estrogen receptor α (ERα) positive breast cancers, and high expression of CTR9 correlates with poor prognosis and tamoxifen resistance." (PMID 35137163, 2022). "Integrative analyses of the ChIP-seq and microarray gene expression data sets identified the primary ERα and Ctr9 target genes, which have prognostic value of breast cancer outcome." (PMID 27829357, 2016). "We showed that Ctr9 acts as a master regulator of the gene transcription program in ERα-positive breast cancer cells by affecting the global occupancy of ERα and RNAPII." (PMID 27829357, 2016). "Our studies have demonstrated the involvement of Ctr9, a key scaffold subunit of human PAFc, in ERα-positive breast cancer progression and ERα target gene expression." (PMID 27829357, 2016). "In line with our previous finding that Ctr9 is highly expressed in ERα-positive breast cancer, the Ctr9 signature is also enriched in ERα-positive breast tumors." (PMID 27829357, 2016). "To investigate the estrogen and Ctr9 mediated transcription regulation in ERα-positive breast cancer cells, we used the MCF7-tet-on-shCtr9 inducible knockdown cell line previously developed in our lab as a model system." (PMID 27829357, 2016). "Taken together, these integrative analyses provided a deeper understanding of estrogen and Ctr9 regulated transcriptome in ERα-positive breast cancer cells." (PMID 27829357, 2016). "Collectively, our study uncovers a unique mechanism by which a transcriptional elongation factor demarcates the PRC2-mediated H3K27me3 domains in breast cancer cells and provides a molecular basis for therapeutically targeting CTR9-low breast tumors with EZH2 inhibitors." (PMID 35137163, 2022). "Therefore profiling the genome-wide RNAPII occupancy would provide a direct readout of transcriptional activity and thus yield mechanistic insights into the transcriptional regulation by estrogen and Ctr9 in ERα-positive breast cancer." (PMID 27829357, 2016). "We had previously identified Ctr9, the key scaffold subunit of the human RNA polymerase II (RNAPII) associated factor complex (PAFc), as a key factor regulating a massive ERα target gene expression and ERα-positive breast cancer growth." (PMID 27829357, 2016).
breast carcinoma (continued). "Given that ERα-positive breast cancer depends on estrogen for growth and target gene transcription regulation, we next sought to identify primary Ctr9 targets in the presence of E2 by comparing genes with RNAPII binding decreased by Ctr9 KD and genes with decreased expression upon Ctr9 KD." (PMID 27829357, 2016). "Our previous study implies that Ctr9 might function independently of the other subunits of PAFc in regulating target gene expression and breast cancer progression." (PMID 27829357, 2016). "However, the global control of Ctr9 on ERα occupancy and RNAPII recruitment awaits investigation to deeply understand the functional significance of Ctr9 in ERα transcription network in breast cancer." (PMID 27829357, 2016). "Kaplan-Meier analysis demonstrated that high expression levels of the Ctr9 signature strongly associates with poor overall survival in ERα-positive, lymph node-negative breast cancer patients, further highlighting the functional significance of Ctr9 in human breast cancer." (PMID 27829357, 2016). "We found that loss of Ctr9 dramatically decreases the global occupancy of ERα and RNAPII, highlighting the significance of Ctr9 in regulating estrogen signaling in ERα-positive breast cancer cells." (PMID 27829357, 2016). "Furthermore, all three groups of ERα cistrome displayed overlapping yet different DNA motif enrichment, suggesting that Ctr9 might affect or cooperate with other factors to regulate ERα action and estrogen signaling in ERα-positive breast cancer." (PMID 27829357, 2016). "Interestingly, our results also showed that UBR5 can not only down-regulate the expression of the CDC73 in breast cancer cells, but also additional PAF1C subunits PAF1, CTR9, and LEO1." (PMID 35551175, 2022). "Besides, Ctr9 KD also decreased RNAPII occupancy at 1583 non-E2-responsive genes, suggesting that Ctr9-dependent RNAPII chromatin occupancy is not restricted to the estrogen regulated genes in breast cancer." (PMID 27829357, 2016). "We speculate that CTR9 levels, rather than ER status, is a predictive biomarker for PRC2 dependency in breast cancer cells." (PMID 35137163, 2022).
breast tumor (2 papers, 2016 to 2022). "The negative correlation between CTR9 and PRC2.1 facultative subunits (PHF1/MTF2/PHF19 and EPOP) at the mRNA level was also observed in 817 ER-positive primary breast tumor samples in TCGA." (PMID 35137163, 2022).
glioma (2 papers, 2023). A benign or malignant brain and spinal cord tumor that arises from glial cells (astrocytes, oligodendrocytes, ependymal cells). "Cell experiment showed that modulation of the JAK2/STAT3 pathway by CTR9 was found to promote proliferation, migration, and invasion of glioma cells." (PMID 37766864, 2023). "Furthermore, for assessing the function of CORE, MYC and PAF modules in cancer cells, Nanog (for CORE module), c-Myc (for MYC module) and Ctr9 (for PAF module) were knocked down in glioma cell line U87 respectively." (PMID 37059858, 2023).
acute myeloid leukemia (1 paper, 2016). Acute myeloid leukemia (AML) is a group of neoplasms arising from precursor cells committed to the myeloid cell-line differentiation. "Moreover, ChIP-seq analyses in human acute myeloid leukemia THP1 cells showed that PAF1 occupancy generally overlaps with the promoter-proximal RNAPII peaks whereas Ctr9 occupancy does not, reinforcing the PAFc independent functions of Ctr9." (PMID 27829357, 2016).
Alzheimer disease (1 paper, 2011). A progressive, neurodegenerative disease characterized by loss of function and death of nerve cells in several areas of the brain leading to loss of cognitive function such as memory and language. "Novel candidates are associated with neurodegenerative disorders including Alzheimer's disease (VSNL1), prion disease (SCRG1, HSPH1, HSPA5 and CTR9) and age-related degeneration (GAS6 and GNG11)." (PMID 21569303, 2011).
colon cancer (1 paper, 2024). "To determine the mechanism underlying colon cancer stemness control by PAF1C, we further generated TetOff cells conditionally expressing amiRNAs against CDC73 and CTR9." (PMID 38182897, 2024).
colorectal cancer (1 paper, 2025). A primary or metastatic malignant neoplasm that affects the colon or rectum. "Notably, SRSF3, CPSF3, FIP1L1, CTR9, NUDT21, and CSTF2, among others, were found to exhibit a more significant contribution to the differential 3′-UTR gene expression in colorectal cancer." (PMID 40702779, 2025).
cyst (1 paper, 2016). A sac-like closed membranous structure that may be empty or contain fluid or amorphous material. "However, germline clones of a Ctr9 null mutation appear to proceed through the early steps of cyst development without obvious defects in nuclear morphology." (PMID 27678520, 2016).
pancreatic carcinoma (1 paper, 2024). "We concluded that the critical function of CTR9 in pancreatic carcinoma is to protect tumor from eradication by the immune system." (PMID 38365788, 2024).
cancer (9 papers, 2016 to 2025). A tumor composed of atypical neoplastic, often pleomorphic cells that invade other tissues. "In our analysis, we found that seven out of 10 pedigrees had potential co-segregated pathogenic variants in known cancer-associated genes, including CHEK2, ATM, MRE11, and CTR9, and some other cancer-associated genes, such as IGF2R and CHRNA3." (PMID 31214250, 2019). "Mutations in CDC73 and CTR9 have been identified in cancer and telomere function is often affected in cancer." (PMID 29145644, 2018). "Finally, human CDC73 and CTR9 genes are frequently found mutated in cancer, and are the only PAF1 complex genes to be currently classified as tumour suppressors." (PMID 29145644, 2018). "In a similar manner to the PAF1 knockdown, CDC73 or CTR9 knockdown inhibited cell proliferation, reduced the expression levels of most cancer stem cell marker genes including LGR5 and ID1, and increased those of KRT20 and MUCs." (PMID 38182897, 2024). "During our analysis, we also identified some likely pathogenic variants in recently established cancer predisposition genes, such as MRE11 and CTR9." (PMID 31214250, 2019). "Against the backdrop of growing evidence for a tight interplay between Paf1C/Ctr9 and Notch signaling, as well as cell cycle gene expression, it is not surprising that Paf1C/Ctr9 is emerging as an important factor in human cancer." (PMID 27520958, 2016). "However, little is known about how CDC73 and CTR9 function as tumor suppressors, particularly since mutations in the genes encoding the other members of the Paf1 complex have not yet been linked to the development of cancer." (PMID 29320491, 2018). "Since CTR9 depletion generates therapeutic vulnerability to pharmacological inhibition of PRC2, the CTR9 expression levels may be used as a biomarker for predicting PRC2 dependency and EZH2 inhibitor sensitivity in broad cancer types." (PMID 35137163, 2022).
tumor (5 papers, 2018 to 2025). "The data show that depletion of CTR9 in the tumor tissue causes the loss of signals that restrain T-cell function and induce a specific activation of T-cell mediated immune responses." (PMID 38365788, 2024). "To test whether escape from immune surveillance is the critical function of PAF1c in KPC tumors, we performed histological analyses and found that depletion of CTR9 caused an increase in the number of multiple types of immune cells in the tumor tissue." (PMID 38365788, 2024). "Singular cases of familial predisposing mutations were: A patient with a heterozygous deletion of CTR9 exons 8–9, that became homozygous due to LOH 11p in the left and right tumor." (PMID 40340749, 2025). "The analysis showed that depletion of CTR9 led to an often complete tumor regression, documented by very large decreases in luciferase activity such that many tumors were virtually undetectable by luciferase imaging after CTR9 depletion." (PMID 38365788, 2024). "Seven days later, we determined the tumor status using luciferase imaging and added doxycycline to the food to induce CTR9 depletion." (PMID 38365788, 2024). "Reflecting these tumor cell-intrinsic changes, depletion of CTR9 induced a specific increase in the number of T-cells and cDC1 dendritic cells, which present antigen to T-cells, and an activation of CD8-positive T-cells." (PMID 38365788, 2024). "Moreover, CTR9 was discovered to be a central regulator of estrogen and may act as a tumor suppressor." (PMID 37566603, 2023). "Consistently, exposure of mice to AZD6738 significantly enhanced the percentage of tumor cells that stained positive for phosphorylated KAP1 and H2AX in CTR9-depleted tumors while treatment of control animals with AZD6738 did not induce a significant increase in KAP1 or H2AX phosphorylation." (PMID 38365788, 2024). "Depletion of CTR9, a core subunit of PAF1c, in a mouse model of pancreatic ductal adenocarcinoma (PDAC) resulted in significant tumor regression, with many mice having no detectable tumor signal." (PMID 40488968, 2025).
infection (1 paper, 2011). The state of being infected such as from the introduction of a foreign agent such as serum, vaccine, antigenic substance or organism. "A striking observation is that enhancement of infection results after independent knockdown of 3 components of the PAF1 complex (PAF1c), PAF1, CTR9 and RTF1 (A3, Z scores from the initial screen of 4.4, 3.3 and 8.5 respectively)." (PMID 22082156, 2011).
CTR9 also shares sentences with these, for which no sentence is quoted: hyperthyroidism (1 paper); parathyroid carcinomas (1); prion disease (1).